OSM (oncostatin M)
Diseases named in the same sentence as OSM in open-access papers (continued):
Sharing a sentence is not in itself a finding about the gene and the disease.
brain cancer (1 paper, 2023). A primary or metastatic malignant neoplasm affecting the brain. "Overexpression of OSM and/or OSMRβ is seen more commonly in a multitude of advanced tumors and is linked to decreased patient survival in several cancer types, including breast, cervical, colon, pancreatic, lung, and brain cancer." (PMID 37841259, 2023).
brucellosis (1 paper, 2024). Brucellosis is a bacterial infection that spreads from animals to people via unpasteurized dairy products or by exposure to contaminated animal products or infected animals. "As the major contributor of potential inflammatory storm, many inflammatory response genes (e.g., ITGB2, OSM, FPR1, CEBPB, NINJ1) and canonical pro‐inflammatory cytokines (e.g., CXCL8, CCL3, CCL4, TNF, IL1B, S100A12) were expressed at higher levels in brucellosis patients than in healthy donors." (PMID 39135683, 2024).
carcinoma in situ (1 paper, 2023). "These preliminary studies evaluating OSM in testicular cancer suggest a possible role for OSM in Leydig cell differentiation and function of mature Leydig cells and recognize the presence of OSM in Leydig cell carcinoma and carcinoma in situ." (PMID 37841259, 2023).
cervical squamous cell carcinoma (1 paper, 2021). A squamous cell carcinoma arising from the cervical epithelium. "The overexpression of OSM and OSMR in cervical squamous cell carcinoma (SCC) can also cause a variety of malignant effects, including infiltration and production of angiogenic factors and associated with poor clinical outcomes." (PMID 34422217, 2021).
cholangiocarcinoma (1 paper, 2023). A carcinoma that arises from the intrahepatic biliary tree (intrahepatic cholangiocarcinoma) or from the junction, or adjacent to the junction, of the right and left hepatic ducts (hilar cholangiocarcinoma). "In cholangiocarcinomas, OSM expression controls immune cell survival and tumor invasion." (PMID 38034950, 2023).
Cirrhosis (1 paper, 2022). A chronic disorder of the liver in which liver tissue becomes scarred and is partially replaced by regenerative nodules and fibrotic tissue resulting in loss of liver function. "OSM is up-regulated in cirrhosis, where it has been associated with enhanced collagen production by stellate cells." (PMID 36552746, 2022).
clear cell renal cell carcinoma (1 paper, 2023). "Currently, the role of oncostatin M (OSM) in clear cell renal cell carcinoma (ccRCC) has not been investigated." (PMID 38034950, 2023).
dementia (1 paper, 2019). Loss of intellectual abilities interfering with an individual's social and occupational functions. "Our study highlights the changes and potential contributions of several chemokines (CXCL1, CCL3, CXCL5, CXCL6, CCL3, CCL19), interleukins (IL8, IL6-RA, IL18-BP), and other immune markers (OSM, ALCAM, OPG, CHIT1, YKL-40, STAMBP, MMP-9, MMP-10) in the prodromal and dementia phases of AD." (PMID 31694701, 2019).
diabetic nephropathy (1 paper, 2017). "NCF1, OSM, SMAD1 and TGFB1 provide protection against diabetic nephropathy, SYVM1 and TXNIP protect against diabetic retinopathy and BDNF in ameliorating the diabetic neuropathy." (PMID 28761062, 2017).
dilated cardiomyopathy (1 paper, 2015). Cardiomyopathy which is characterized by dilation and contractile dysfunction of the left and right ventricles. "By these means we have identified oncostatin M as a major modulator of cardiac remodeling, as well as a promising therapeutic target in dilated cardiomyopathy." (PMID 26236717, 2015). "The increased presence of macrophages combined with elevated levels of various chemokines and cytokines such as MCP-1 (monocyte chemotactic protein-1), TNF-α, and oncostatin M during the pathogenesis of dilated cardiomyopathy underscores the contribution of cardiac inflammation." (PMID 26236717, 2015).
ductal carcinoma (1 paper, 2021). "OSM signaling and LOXL2 nuclear localization have been implicated in promoting epithelial to mesenchymal transition in ductal carcinoma cells." (PMID 34011405, 2021).
endometritis (1 paper, 2026). An acute or chronic, usually bacterial infectious process affecting the endometrium. "Our findings highlight the therapeutic potential of LIF and OSM as modulators of uterine immune homeostasis and macrophage plasticity modulating and mitigating LPS-acute endometritis and preserving endometrial integrity." (PMID 42256298, 2026).
endothelial dysfunction (1 paper, 2022). In vascular diseases, endothelial dysfunction is a systemic pathological state of the endothelium (the inner lining of blood vessels) and can be broadly defined as an imbalance between vasodilating and vasoconstricting substances produced by (or acting on) the endothelium. "OSM, MCP‐2, TGF‐α, and CXCL6 are likely to have an association with endothelial dysfunction and some are mostly or additionally involved in IR (MCP‐1, FGF‐21, TRAIL, and ADA) or insulin metabolism (TNFSF14/LIGHT)." (PMID 36467791, 2022). "Some of the identified proteins do not have a clear role in endothelial inflammation, but we consider OSM, MCP‐2, TGF‐α, and CXCL6 to have an association with endothelial dysfunction when the proteomic results are considered together with our clinical data." (PMID 36467791, 2022).
eosinophilia (1 paper, 2020). "We and others have shown overexpression of OSM, or administration of OSM protein results in a Th2-like phenotype (eosinophilia and IL-4, IL-5, and IL-13 cytokine production) with an associated Arg1+ alternatively activated macrophage accumulation in the C57Bl/6 mouse lung." (PMID 33376451, 2020).
Ewing sarcoma (1 paper, 2023). A small round cell tumor that lacks morphologic, immunohistochemical, and electron microscopic evidence of neuroectodermal differentiation. "Very little evidence exists for OSM and Ewing sarcoma (ES); however, the OSM gene has been shown to be differentially methylated in an ES microarray dataset (65% compared to healthy patients), although this did not significantly correlate with survival rate." (PMID 37841259, 2023).
glomerulonephritis (1 paper, 2021). A renal disorder characterized by damage in the glomeruli. "Oncostatin-M participated in immune regulation and lack of oncostatin-M resulted in increased levels of anti-dsDNA and glomerulonephritis." (PMID 33800255, 2021).
gout (1 paper, 2024). A condition characterized by painful swelling of the joints, which is caused by deposition of urate crystals. "Firstly, the proteins identified as differentially expressed between gout and healthy controls, such as VEGF-A, MMP-1, TGF-α, and OSM, show high discriminative power and may serve as potential biomarkers for gout diagnosis." (PMID 39611154, 2024).
hepatic cancer (1 paper, 2022). "Taken together, these data strongly indicate that OSM determines a phenotypic switch in hepatic cancer cells, making them more invasive and capable of orchestrating the formation of new blood vessels." (PMID 35064579, 2022).
Hepatic steatosis (1 paper, 2021). Steatosis is a term used to denote lipid accumulation within hepatocytes. "We recently found that the plasma levels of CSF‐1, OSM, and FGF‐21 are significantly associated with hepatic steatosis (Lovric et␣al, 2018)." (PMID 34694070, 2021).
hepatitis C virus infection (1 paper, 2017). A viral infection caused by the hepatitis C virus. "Thereby, our data extend recent findings which showed a cross‐talk of OSM and IFNs in the protection from hepatitis C virus infection 19, 20, 21 by elucidating a novel, yet unaddressed mechanism of OSM‐mediated immunomodulatory activities." (PMID 28560754, 2017).
histiocytic lymphoma (1 paper, 2020). "OSM is a cell growth regulating polypeptide that was first isolated from the serum-free supernatants of U937 histiocytic lymphoma cells." (PMID 33216732, 2020). "Oncostatin M (OSM) is a cytokine secreted by differentiated histiocytic lymphoma cells." (PMID 33216732, 2020).
HIV-1 infection (1 paper, 2016). The type species of lentivirus and the etiologic agent of acquired immunodeficiency syndrome (AIDS). "In a co-culture study of HIV-1 infected T cells (CEM) and latently KSHV infected B cells (BCBL-1), several cytokines including oncostatin M (OSM), hepatocyte growth factor/scatter factor (HGF/SF), and IFN-γ were found to be induced in response to HIV-1 infection in CEM or BCBL-1 cells." (PMID 26913028, 2016).
Hyperkeratosis (1 paper, 2023). Hyperkeratosis is a histopathological term defining a thickened stratum corneum and may be present in many different skin conditions, with many possible overlaps. "Oncostatin M (OSM) is a member of the IL-6 cytokine family that plays a significant role in various pathological processes in the skin, including inflammation, hyperkeratosis, and fibrosis." (PMID 38077377, 2023).
idiopathic intracranial hypertension (1 paper, 2021). "OSM was recently identified as a potential CSF marker of general CNS inflammation, although interestingly, the study included iNPH patients and patients with idiopathic intracranial hypertension as the non-inflamed controls." (PMID 34863228, 2021).
infarction (1 paper, 2024). A localised pathological necrosis of tissue resulting from obstruction of the blood supply usually by a thrombus, an embolus, or vascular torsion. "MINOCA patients showed a greater increase in pro-inflammatory cytokines PlGF, oncostatin M, IL-20, and CCL-15 sVCAM-1 during the early post-infarction period and in CCL-21, sVCAM-1, oncostatin M, and PlGF after one year." (PMID 39595023, 2024).
injury (1 paper, 2022). Damage inflicted on the body as the direct or indirect result of an external force, with or without disruption of structural continuity. "Spinal cord injuries and traumatic brain injuries can also result in development of HO, Macrophages may secrete oncostatin M to mediate inflammation when spinal cord injury occurs." (PMID 35530413, 2022).
irritable bowel syndrome (1 paper, 2022). Irritable bowel syndrome (IBS) is a chronic functional condition of the lower gastrointestinal (GI) tract characterized by abdominal pain or discomfort and disordered bowel habit (diarrhea, constipation, or fluctuation between the two). "OSM and TNF-α are inflammatory cytokines elevated in CDI and irritable bowel syndrome (IBD)." (PMID 36557633, 2022).
kidney stone (1 paper, 2020). "From these findings, OSM seems to regulate inflammation through the production of inflammatory cytokines rather than by recruitment of M1 macrophages in the process of kidney stone formation." (PMID 33051515, 2020). "In the kidneys of OSMRβ−/− mice, there was considerably less formation of GOx-induced crystal deposits than in WT mice on day 6, suggesting that OSM signaling may promote the formation of renal crystal deposits in the process of kidney stone formation." (PMID 33051515, 2020).
laryngeal carcinoma (1 paper, 2022). Carcinoma that arises from the laryngeal epithelium. "In this study, we explored the role of ING4 and OSM on enhanced anti‐tumour activity for human laryngeal cancer in vitro and in vivo and also elucidation of the underlying mechanism." (PMID 35075768, 2022). "In order to prove whether ING4 and OSM have a significant influence on the growth and apoptosis of human laryngeal cancer Hep‐2 cells, we used recombinant Ad vectors for gene transfer." (PMID 35075768, 2022). "Finally, the underlying mechanism of recombinant adenoviruses co‐expression of ING4 and OSM in laryngeal cancer has not been fully clarified in this study." (PMID 35075768, 2022). "However, the role of recombinant adenoviruses co‐expressing ING4 and OSM (Ad‐ING4‐OSM) in anti‐tumour activity of laryngeal cancer has not yet been identified." (PMID 35075768, 2022).
lymph node metastasis (1 paper, 2022). "Significant association was found between increased oncostatin M expression and the depth of myometrial invasion, lymph node metastasis, advanced disease stage (stages III or IV) and poor histological differentiation (grade 3)." (PMID 34951691, 2022).
malignant glioma (1 paper, 2018). A grade III or grade IV glioma arising from the central nervous system. "Oncostatin M (OSM), a cytokine belonging to the interleukin-6 family, has been shown to be increased in a variety of cancers, including malignant glioma." (PMID 29168083, 2018).
mastitis (1 paper, 2025). Inflammation of breast tissue during lactation or postpartum due to an obstructed duct or infection. "DEGS such as IL10, CCL5, IL1B, OSM, TNFRSF1B, IL7, and CCR3, among others, implicated in these pathways, may play a crucial role in the development of subclinical mastitis in Bactrian camels, though further analysis is needed to explore their potential functions." (PMID 40005880, 2025).
metastatic cancer (1 paper, 2019). A carcinoma which has spread from the original site of growth to another anatomic site. "Individually, inflammatory cytokines such as OSM, IL-6, and IL-1β have been shown to promote effects associated with metastatic cancer." (PMID 31007849, 2019).
myeloid neoplasm (1 paper, 2013). Proliferation of myeloid cells originating from a primitive stem cell. "OSM has been reported to act as a growth factor in myeloid neoplasms and has also been shown to inhibit proliferation of numerous malignant cell lines, including murine M1 myeloid leukemic cells." (PMID 23826213, 2013).
myopia (1 paper, 2023). "This analysis indicated that INFG, TNF, IL1B, EGF, HGF and OSM would be predicted to stimulate recovery from induced myopia (activators)." (PMID 38390290, 2023).
neuroendocrine neoplasm (1 paper, 2021). Endocrine tumors, also referred to as neuroendocrine tumors (NETs), are defined by a common phenotype which is characterized by the expression of general markers (neuron specific enolase, chromogranin, synaptophysin) and hormone secretion products. "Our data suggest that transcription factor 3/HNF1A-AS1/Oncostatin M axis inhibits the tumorigenesis and metastasis of gastroenteropancreatic neuroendocrine neoplasms via transforming growth factor-β signaling." (PMID 34037532, 2021).
non-alcoholic-fatty liver disease (1 paper, 2019). "In vivo and in vitro experiments were performed to analyze the expression of OSM and OSM-receptor (OSMR) in three murine models of non-alcoholic-fatty liver disease (NAFLD) and -steatohepatitis (NASH) and in human NASH patients as well as the action of OSM on phenotypic responses of human MFs." (PMID 31861914, 2019).
ovarian dysfunction (1 paper, 2023). The inability of the ovaries to function. "Among the genes we identified through coexpression of three datasets, PNPLA3, MVD, MMP9, oncostatin M (OSM), LCK, triggering receptor expressed on myeloid cells 1 (TREM1), FADS2, proprotein convertase subtilisin/kexin type 9 (PCSK9), and C3 are involved in lipid metabolism and ovarian dysfunction." (PMID 37537636, 2023).
pancreatic ductal adenocarcinoma (1 paper, 2023). An infiltrating adenocarcinoma that arises from the epithelial cells of the pancreas. "Interleukin 6 (IL-6), Oncostatin M (OSM), and downstream effector STAT3 are pro-tumorigenic agents in pancreatic ductal adenocarcinoma (PDAC)." (PMID 36495330, 2023).
Pancytopenia (1 paper, 2014). An abnormal reduction in numbers of all blood cell types (red blood cells, white blood cells, and platelets). "In this study, we show that Oncostatin M (OSM) knock out mice exhibited pancytopenia advancing fatty marrow with age." (PMID 25551451, 2014).
Parkinson disease (1 paper, 2025). A progressive degenerative disorder of the central nervous system characterized by loss of dopamine producing neurons in the substantia nigra and the presence of Lewy bodies in the substantia nigra and locus coeruleus. "Other notable observations include the downregulated levels of OSM, MNDA, AZU1 and MMP9, which are well-known neuroinflammatory markers, proven in several Parkinson’s disease models." (PMID 39816194, 2025).
perinatal disease (1 paper, 2024). A condition affecting an unborn or newly born individual, where the perinatal period is defined in humans as commencing at 22 completed weeks (154 days) of gestation and ending seven completed days after birth. "OSM/OSMR signaling plays an important role in inflammation, hematopoiesis, development, and is increasingly recognized as an important factor in cancer progression, but is still underrepresented in perinatal disease studies." (PMID 39148025, 2024).
periodontal disease (1 paper, 2023). "OSM and other cytokines play an important role in the progression of periodontal disease, a gum infection typically caused by poor brushing and flossing habits." (PMID 37841259, 2023). "CXCL10 and ICAM-1 expression were both suppressed when inhibitors of NF-κB and STAT3 were introduced, indicating that OSM-mediates STAT3 signaling and IL-1β-mediated NF-κB signaling may promote infiltration and retention of Th1 cells, leading to periodontal disease." (PMID 37841259, 2023).
polycystic ovary syndrome (1 paper, 2024). A disorder that manifests as multiple cysts on the ovaries. "In this research, the concentration of oncostatin M in the plasma was strikingly low in those with polycystic ovary syndrome, and this was significantly associated with the hormonal and metabolic features of polycystic ovary syndrome." (PMID 38397957, 2024). "It was found that oncostatin M and its receptor levels in follicle fluid were significantly lower in patients with polycystic ovary syndrome." (PMID 38397957, 2024). "It was also observed that plasma C-reactive protein levels were negatively correlated with the plasma levels of oncostatin M in patients with polycystic ovary syndrome." (PMID 38397957, 2024). "Oncostatin M levels were significantly lower, but C-reactive protein levels were substantially higher in the polycystic ovary syndrome group than in the control group (p = 0.002, p = 0.001, respectively)." (PMID 38397957, 2024). "It was shown in this study that oncostatin M levels were markedly lower in polycystic ovary syndrome patients compared to the control group." (PMID 38397957, 2024). "This study is one of the first to investigate the levels of oncostatin M in patients with polycystic ovary syndrome, filling a gap in the existing scientific literature on the close relationship between oncostatin M and human oocytes, granulosa cells, and ovulation." (PMID 38397957, 2024). "More thorough studies on the relationship between oncostatin M and the secretion of gonadotropin-releasing hormone could help us better understand the role of oncostatin M in the development of polycystic ovary syndrome." (PMID 38397957, 2024). "A significant negative correlation was also found between the ratio of luteinizing hormone to follicle-stimulating hormone and levels of oncostatin M. Taken together, it could be argued that oncostatin M may interact through the neuroendocrine system in polycystic ovary syndrome." (PMID 38397957, 2024).
polyp (1 paper, 2023). A usually exophytic mass attached to the underlying tissue by a broad base or a thin stalk. "OSM protein and OSM mRNA are overexpressed in CRSwNP compared with controls and seem to act both on the fibroblastic and epithelial components of polyp tissues as well as on TJs." (PMID 37047067, 2023).
preeclampsia (1 paper, 2013). Preeclampsia is a hypertensive disorder of pregnancy that is characterized by new-onset hypertension with proteinuria presenting after 20 weeks of gestation, and depending on mild or severe forms may initially present with severe headache, visual disturbances, and hyperreflexia. "Another possibility is that the increased expression of OSM in preeclampsia may not be related to the effects of OSM on migration, proliferation, and invasion of EVTs, but instead could be related to the other effects of OSM." (PMID 24060241, 2013).